PAH (phenylalanine hydroxylase)
Diseases named in the same sentence as PAH in open-access papers (continued):
Sharing a sentence is not in itself a finding about the gene and the disease.
phenylketonuria (continued). "Phenylketonuria (PKU, OMIM # 261200) is the most common inborn error of amino acid metabolism and is caused by a defect in phenylalanine (Phe) hydroxylase (PAH; EC 1.14.16.1) or in its cofactor, tetrahydrobiopterin (BH4)." (PMID 30453665, 2018). "Phenylketonuria (PKU; OMIM 261600) is an autosomal recessive disease, which results in a toxic excess of Phenylalanine (Phe) due to the loss of function of phenylalanine hydroxylase (PAH; EC 1.14.16.1) with an incidence of 1:15,000 live births." (PMID 28282402, 2017). "Finally, the model was used to explore the genetic condition of maternal phenylketonuria, where lack of phenylalanine hydroxylase causes an excess level of phenylalanine that can affect fetal development and function." (PMID 27045077, 2016). "Phenylketonuria (PKU; MIM 261600), an autosomal recessive disorder of Phenylalanine (Phe) metabolism, is mainly caused (98 % of cases) by deficient activity of the hepatic enzyme L-phenylalanine-4-hydroxylase (PAH; EC 1.14.16.1), due to mutations in the PAH gene (NM 000277.1)." (PMID 27612877, 2016). "Phenylketonuria (PKU, OMIM 261600) is the most frequent and important inherited metabolic disease, caused by deficiency of hepatic phenylalanine hydroxylase (PAH, EC 1.14.16.1)." (PMID 27786189, 2016). "Phenylketonuria (PKU; MIM 261600) is a rare inherited disorder of phenylalanine (Phe) metabolism caused by a deficiency of the enzyme phenylalanine hydroxylase (PAH; EC 1.14.16.1)." (PMID 26084935, 2015). "Phenylketonuria (PKU, OMIM 261600) is an autosomal recessive disorder caused by a deficient hepatic phenylalanine hydroxylase (PAH) activity." (PMID 26666653, 2015). "Phenylketonuria (PKU, ORPHA79254, MIM 261600) is a genetic disorder caused by mutations in the gene coding for phenylalanine hydroxylase (PAH; EC 1.14.16.1)." (PMID 25758373, 2015). "The classic example of this type of pleiotropy, phenylketonuria (PKU), involves a change in phenylalanine hydroxylase, the enzyme that converts L-phenylalanine to L-tyrosine." (PMID 24282555, 2013). "Phenylketonuria (PKU; MIM 261600) is an autosomal recessive inborn error of phenylalanine metabolism caused by a deficiency of the enzyme phenylalanine hydroxylase (PAH; EC 1.14.16.1)." (PMID 21708003, 2011). "Phenylketonuria (PKU; OMIM 261600) is an inborn error of amino acid metabolism resulting from deficiency of phenylalanine hydroxylase, the key enzyme for phenylalanine metabolism." (PMID 21152388, 2010). "The c.1199 + 502 A > T variant of the phenylalanine hydroxylase (PAH) gene, which is the most frequently reported deep intronic variant involved in phenylketonuria (PKU), is mainly observed in patients with classical or mild PKU." (PMID 40420248, 2025). "Phenylketonuria (PKU, Følling disease, OMIM #261600), is an autosomal recessive disorder of phenylalanine (Phe) metabolism caused by biallelic pathogenic variants in the PAH gene encoding phenylalanine hydroxylase (PAH, EC 1.14.16.1, OMIM *612349)." (PMID 40293582, 2025). "Phenylketonuria (PKU; OMIM (Online Mendelian Inheritance in Man) #261600) is an inborn error of the phenylalanine hydroxylase with an incidence of 19.3/100,000 newborns in 2020 in Germany." (PMID 40026687, 2025). "Patients with phenylketonuria (PKU) who retain residual phenylalanine hydroxylase (PAH) activity may benefit from sapropterin dihydrochloride (sapropterin) administration." (PMID 40426720, 2025). "In phenylketonuria (PKU), a condition characterized by the significant reduction in the activity of PAH and the accumulation of phenylalanine, synthetic PAL pills were used to enhance the metabolism of phenylalanine into trans-cinnamate." (PMID 38516193, 2024). "Phenylketonuria (PKU, OMIM# 261600) is a common autosomal recessive inherited metabolic disease with an inborn error of phenylalanine (Phe) metabolism, which is caused by pathogenetic variants in the phenylalanine hydroxylase (PAH) gene." (PMID 37004080, 2023).
phenylketonuria (continued). "In 2001, a case of a 5-year-old girl heterozygous for a large de novo deletion at 12q23 (involving the IGF1, PAH, and ASCL1 genes) was described, resulting in phenylketonuria." (PMID 37958729, 2023). "Phenylketonuria (PKU) manifests only in the presence of mutations that render both copies of the phenylalanine hydroxylase enzyme non-functional and a diet that includes phenylalanine." (PMID 35749392, 2022). "Phenylketonuria (PKU) is a common congenital metabolic disorder (1 in 10,000–14,000 live births) in which phenylalanine metabolism is defected due to allelic variations in the phenylalanine hydroxylase (PAH) gene." (PMID 36004917, 2022). "The first disease screened for in neonates using dried blood tablets was phenylketonuria (PKU); the detection method reveals whether a neonate lacks phenylalanine hydroxylase by assessing the amount of the enzyme present." (PMID 35419325, 2022). "Phenylketonuria (PKU) (PKU, OMIM—Online Mendelian Inheritance in Man # 261,600) is a rare inherited metabolic disorder caused by mutations in the phenylalanine hydroxylase gene leading to phenylalanine hydroxylase deficiency and an inability to convert phenylalanine into tyrosine." (PMID 36296952, 2022). "Phenylketonuria (PKU; MIM #261600) is an inborn error of metabolism caused by the deficiency of phenylalanine hydroxylase (PAH, EC 1.14.16.1), the hepatic enzyme that converts phenylalanine (Phe) into tyrosine (Tyr), using tetrahydrobiopterin (BH4) as a coenzyme." (PMID 34836270, 2021). "In phenylketonuria (PKU) patients, a genetic defect in the enzyme phenylalanine hydroxylase (PAH) leads to elevated systemic phenylalanine (Phe), which can result in severe neurological impairment." (PMID 34711827, 2021). "Phenylketonuria (PKU; OMIM #261600) is an autosomal recessive genetic disorder caused by the deficiency in the hepatic enzyme phenylalanine hydroxylase (PAH; OMIM #612349) that converts phenylalanine into tyrosine requiring the cofactor tetrahydrobiopterin (BH4)." (PMID 33465300, 2021). "Phenylketonuria (PKU; OMIM 261600) is a rare inherited metabolic disease characterized by the absence of the liver enzyme phenylalanine (Phe) hydroxylase (PAH; EC 1.14.16.1) that converts Phe into tyrosine." (PMID 31484352, 2019). "Phenylalanine hydroxylase (PAH; EC 1.14.16.1) deficiency commonly called phenylketonuria (PKU) is an autosomal recessive inborn error of Phe metabolism resulting in an inability to synthesize Tyr and elevated concentrations of its precursor Phe in blood and brain." (PMID 31650703, 2019). "Phenylketonuria (PKU; OMIM 261600) is an inborn error of metabolism, characterized by impaired activity of the hepatic enzyme phenylalanine hydroxylase (PAH; EC 1.14.16.1) that normally converts phenylalanine (Phe) to tyrosine." (PMID 30157945, 2018). "Sapropterin dihydrochloride, a synthetic formulation of BH4, the cofactor for phenylalanine hydroxylase (PAH, EC 1.14.16.1), was initially approved in Europe only for patients ≥4 years with BH4-responsive phenylketonuria." (PMID 28274234, 2017). "Phenylketonuria [PKU, MIM 261600, also referred to as phenylalanine hydroxylase (PAH; EC 1.14.16.1) deficiency] is a rare (prevalence < 1/10,000–1/15,000 births) autosomal recessive disorder characterized by an impairment of the body's ability to metabolize phenylalanine (Phe)." (PMID 27014571, 2016). "Phenylketonuria (PKU; MIM 261600) is an autosomal recessive disorder caused by the deficiency of phenylalanine hydroxylase (PAH, EC 1.14.16.1), a liver enzyme that catalyzes the conversion of phenylalanine (Phe) to tyrosine (Tyr), using tetrahydrobiopterin (BH4) as coenzyme." (PMID 25757997, 2015). "Phenylketonuria (PKU) is the most common inborn error of amino acid metabolism, being due to a deficiency of the enzyme phenylalanine hydroxylase, which normally converts phenylalanine (Phe) to tyrosine (Tyr)." (PMID 23936863, 2013).
phenylketonuria (continued). "Phenylketonuria (PKU) is a rare inborn error of metabolism characterized by high phenylalanine (Phe) concentrations in the blood and brain due to impaired activity of the enzyme phenylalanine hydroxylase." (PMID 39146838, 2024). "One such disorder is phenylketonuria (PKU), an inborn error of amino acid metabolism caused by the defective hydroxylation of phenylalanine (Phe) to tyrosine due to very low or absent activity of the enzyme Phe hydroxylase (PAH)." (PMID 37374973, 2023). "This article highlights the significance of inborn errors of metabolism and focuses specifically on phenylketonuria (PKU), a well-known inheritance disorder caused by the deficiency or absence of phenylalanine hydroxylase (PAH)." (PMID 37456395, 2023). "For instance, the pharmacological chaperone sapropterin (Kuvan) has already been approved as the first non-dietary treatment for patients suffering from phenylketonuria which results from a single amino acid alteration in phenylalanine hydroxylase (PHA)." (PMID 34502079, 2021). "Phenylketonuria (PKU) is a genetic disease, characterized by the total or partialdeficiency of the hepatic enzyme phenylalanine hydroxylase, which is responsible forthe hydroxylation of phenylalanine (PHE) in tyrosine and results in the accumulationof PHE in the body." (PMID 32159642, 2020). "Phenylketonuria (PKU) is an inborn error of amino acid metabolism, due to deficiency or absence of the enzyme phenylalanine hydroxylase, leading to accumulation of blood and brain phenylalanine (Phe)." (PMID 30606267, 2019). "Phenylketonuria (PKU; Online Mendelian Inheritance in Man, OMIM 261,600) is an autosomal recessive disorder of phenylalanine (Phe) metabolism, primarily due to mutations in Phe hydroxylase (PAH) gene, which facilitates conversion of the essential amino acid Phe to tyrosine." (PMID 30154357, 2018). "Acetylphenylalanine is a hazardous metabolite of phenylalanine and is elevated in phenylketonuria due to lack of phenylalanine hydroxylase, the enzyme that converts phenylalanine to tyrosine." (PMID 24015273, 2013). "In the case of phenylketonuria, the enzyme PAH (phenylalanine hydroxylase) activity is decreased by loss of the lncRNA HULC (hepatocellular carcinoma up-regulated long noncoding RNA) without any mutation of PAH." (PMID 40362270, 2025). "In its severe form called phenylketonuria (PKU), the lack of PAH enzyme function may lead to brain damage if left untreated." (PMID 40790757, 2025). "Phenylketonuria (PKU) is a rare, autosomal recessive inborn error of metabolism due to low or absent activity of the enzyme phenylalanine hydroxylase (PAH), required for degradation of phenylalanine to tyrosine." (PMID 33182603, 2020). "Several genetic diseases are linked to the lack of hydroxylation of aromatic amino acids like that of phenylketonuria (PKU) and hyperphenylalaninemia, due to a defect in phenylalanine hydroxylase, an enzyme that converts phenylalanine to tyrosine." (PMID 22312457, 2011). "Erythrocytes loaded with recombinant Chromobacterium violaceum phenylalanine hydroxylase, together with the cofactor tetrahydrobiopterin, were shown to reduced blood phenylalanine levels when administered to wild-type mice, but not when administered to the BTBR Pahenu2 phenylketonuria mouse model." (PMID 32397259, 2020).
Hyperphenylalaninemia (30 papers, 2016 to 2025). "Hyperphenylalaninemia is the most prevalent amino acid metabolism disorder, resulting from a deficiency of either phenylalanine hydroxylase (PAH) or its cofactor, tetrahydrobiopterin (BH4)." (PMID 41357791, 2025). "A deficiency in the PAH enzyme leads to hyperphenylalaninemia, a recessive inherited metabolic condition." (PMID 39339686, 2024). "PKU is the main type of hyperphenylalaninemia and is an autosomal recessive genetic disease caused by mutation of the PAH gene, which encodes phenylalanine hydroxylase." (PMID 37098607, 2023). "Hyperphenylalaninemia (HPA) is an autosomal recessive disorder arising from deficiency of phenylalanine hydroxylase (PAH; EC1.14.16.1), which is an enzyme crucial for the conversion of the amino acid phenylalanine (Phe) to tyrosine (Tyr)." (PMID 38136067, 2023). "Hyperphenylalaninemia (HPA) is the most common amino acid metabolic disease involving phenylalanine hydroxylase (PAH, OMIM*612,349) deficiency or coenzyme tetrahydrobiopterin (BH4) deficiency." (PMID 33980295, 2021). "Hyperphenylalaninemias (HPA) are hereditary autosomal recessive disorders caused by defects in the hepatic phenylalanine hydroxylase (PAH) system." (PMID 33822819, 2021). "Hyperphenylalaninemia, resulting from deficient activity of the enzyme phenylalanine hydroxylase (PAH) in the liver, is the major biochemical sign of PKU." (PMID 32874918, 2020). "It is characterized by the deficiency of the phenylalanine hydroxylase activity, causing plasmatic hyperphenylalaninemia and variable neurological and cognitive impairments." (PMID 28468253, 2017). "Hyperphenylalaninemia (HPA) is a rare inherited metabolic disorder caused by reduced activity of the hepatic enzyme phenylalanine hydroxylase (PAH, EC 1.14.16.1), which catalyses the conversion of phenylalanine (Phe) to tyrosine." (PMID 28274234, 2017). "The main cause of hyperphenylalaninemia (HPA) is the deficiency of the hepatic enzyme phenylalanine hydroxylase (PAH, EC 1.14.16.1), which causes a blockage in the phenylalanine (Phe) degradation pathway, resulting in an accumulation of this amino acid in tissues and blood." (PMID 37421234, 2023). "Hyperphenylalaninemia (HPA) (OMIM 261600) is a recessive inherited metabolic condition caused by the inability to convert Phenylalanine (Phe) to tyrosine (Tyr) due to the total or partial defect of the enzyme phenylalanine hydroxylase (PAH)." (PMID 36010054, 2022). "One of these diseases, hyperphenylalaninemia (HPA), is a hereditary amino acid metabolism disorder caused by the absence or insufficiency of the phenylalanine hydroxylase (PAH) enzyme." (PMID 40151380, 2025). "Among the top ten common variants, DUOX2, SLC22A5, PAH, and ACADS were associated with CH, primary carnitine deficiency, hyperphenylalaninemia, and short-chain acyl-CoA dehydrogenase deficiency, respectively." (PMID 38575986, 2024). "Depending on the concentration of blood phenylalanine and residual phenylalanine hydroxylase (PAH) enzymatic activity, PAH deficiency (OMIM #261600) can present with a range of clinical phenotypes – from mild hyperphenylalaninemia to classic PKU." (PMID 37994477, 2023). "As a cofactor of the phenylalanine hydroxylase (PAH) enzyme that catalyzes the transfer of L-tyrosine (Tyr) from L-phenylalanine (Phe), BH4D causes a build-up of Phe in the blood, which leads to hyperphenylalaninemia (HPA)." (PMID 36583021, 2022). "Aside from PKU caused by mutations in the PAH gene, and HPABH4, related to tetrahydrobiopterin metabolism, HPAs also include DOPA-responsive dystonia and non-BH4-deficient hyperphenylalaninemia." (PMID 33822819, 2021). "Since BH4 is also a cofactor of phenylalanine hydroxylase (PAH), BH4 metabolism disorders are associated with hyperphenylalaninemia (HPA)." (PMID 27798097, 2016).
Hyperphenylalaninemia (continued). "Indeed, a typical clinical feature of BH4 deficiencies is hyperphenylalaninemia because phenylalanine hydroxylase (PAH) is lacking its cofactor to metabolize phenylalanine into tyrosine." (PMID 37251335, 2023).
Intellectual disability (7 papers, 2013 to 2025). "Phenylalanine (l-Phe) is the most important disease of treatable mental retardation that results from phenylalanine hydroxylase enzyme deficiency in newborn babies." (PMID 33467753, 2021).
depression (5 papers, 2016 to 2024). "Tyrosine can be obtained from food or generated (in the liver) from phenylalanine through phenylalanine hydroxylase; its deficiency is strongly involved in the mechanisms of unipolar depression." (PMID 39062797, 2024). "In addition to the significant effect of rTMS on depression scores, these results point to a possible influence of rTMS on the enzyme phenylalanine hydroxylase (PAH), which plays a crucial role in the biosynthesis of neurotransmitter precursors related to geriatric depression." (PMID 31250285, 2019).
Sepsis (5 papers, 2020 to 2026). Sepsis is defined as life-threatening organ dysfunction caused by a dysregulated host response to infection. "In particular, elevated phenylalanine has been associated with hepatic dysfunction and impaired phenylalanine hydroxylase activity in sepsis." (PMID 41209349, 2025). "Plasma levels of Phe are regulated by phenylalanine hydroxylase (PAH); factors such as stress, sepsis, or any causes of hepatic dysfunction may influence the activity of PAH." (PMID 32283658, 2020). "Due to the downregulation of phenylalanine hydroxylase and tyrosine hydroxylase activities during sepsis, the conversion of phenylalanine and tyrosine to dopamine is blocked, and more phenylalanine and tyrosine may be converted to pseudo-neurotransmitters in the brain, affecting nerve signaling." (PMID 39498415, 2024).
Cognitive impairment (4 papers, 2017 to 2023). Abnormal cognition is characterized by deficits in thinking, reasoning, or remembering. "In PKU, elevated plasma levels of phenylalanine, caused by defective phenylalanine hydroxylase (PAH) (i.e., converts phenylalanine into tyrosine) lead to severe cognitive impairment and psychiatric disability." (PMID 38201891, 2023).
hepatoma (4 papers, 2014 to 2025). "Gopalakrishnan and Anderson showed the epigenetic activation of phenylalanine hydroxylase in mouse erythroleukemia cells by the cytoplast of rat hepatoma cells." (PMID 32393195, 2020). "We investigated the situation in vivo analysing the endogenous PAH transcripts in a human liver sample and in hepatoma cell lines Hep3B and HepG2, the latter treated or not with cycloheximide to block nonsense-mediated decay." (PMID 29684050, 2018).
schizophrenia (4 papers, 2014 to 2024). A major psychotic disorder characterized by abnormalities in the perception or expression of reality. "Genetic association studies have suggested an association between schizophrenia and PAH polymorphisms, though the functional impact of these genetic changes is not well understood." (PMID 31551819, 2019). "Additionally, neuroinflammation, implicated in the pathology of schizophrenia can impair the function of the enzyme phenylalanine hydroxylase (PAH), thus leading to the accumulation of Phe." (PMID 38671997, 2024). "Inflammation, increasingly implicated in schizophrenia, can impair the function of the enzyme Phenylalanine hydroxylase (PAH; which catalyzes the conversion of phenylalanine to tyrosine) and thus lead to elevated phenylalanine levels and reduced tyrosine levels." (PMID 24465804, 2014). "This study aimed to compare phenylalanine, tyrosine, and their ratio (a proxy for PAH function) in a relatively large sample of schizophrenia patients and healthy controls." (PMID 24465804, 2014). "Researchers measured plasma Phe in 950 patients with schizophrenia, with a comparable cohort of controls, finding elevated Phe levels, thus supporting the hypothesis of aberrant PAH functioning in schizophrenia." (PMID 38671997, 2024). "In 2014, Okusaga and colleagues measured plasma Phe in 950 patients with schizophrenia compared with 1,000 controls, and found increased Phe and increased Phe/Tyr ratios, suggesting aberrant PAH function in schizophrenia hypothesized to be as a result of neuroinflammation." (PMID 31551819, 2019).